OSR1 (odd-skipped related transcription factor 1)
Diseases named in the same sentence as OSR1 in open-access papers (continued):
Sharing a sentence is not in itself a finding about the gene and the disease.
infection (1 paper, 2022). The state of being infected such as from the introduction of a foreign agent such as serum, vaccine, antigenic substance or organism. "qPCR was employed to investigate the mRNA expression level of OSR1 in the infection group, which was dramatically fewer than in the normal group (p < 0.05)." (PMID 36356076, 2022).
neurological diseases (1 paper, 2019). "This review will give readers an update on the emerging roles of WNK-SPAK/OSR1-CCC signaling pathway in neurological diseases." (PMID 31165006, 2019). "New studies suggest that the WNK-SPAK/OSR1-CCC pathway is also involved in neurological diseases such as ischemic stroke and neuropathy." (PMID 31165006, 2019). "The WNK-SPAK/OSR1-CCCs complex emerges as therapeutic targets for multiple neurological diseases." (PMID 31165006, 2019).
renal disease (1 paper, 2016). "Further studies of the molecular mechanisms involving Osr1 in kidney development, in particular identification of direct downstream target genes and its interaction with other transcription factors and molecular pathways, will significantly improve the understanding of renal disease pathogenesis." (PMID 27442016, 2016).
OSR1 also shares sentences with these, for which no sentence is quoted: edema (2 papers); Gitelman syndrome (2); Hypercalciuria (2); non-alcoholic fatty liver disease (2); adenocarcinoma (1); atherosclerosis (1); Bartter syndrome (1); bladder urothelial carcinoma (1); brain trauma (1); bronchopulmonary dysplasia (1); Central diabetes insipidus (1); cerebral edema (1); cervical squamous cell carcinoma (1); cholangiocarcinoma (1); cognitive disorder (1); colon adenocarcinoma (1); colorectal cancer (1); diabetes insipidus (1); Down syndrome (1); glomerular diseases (1); heart failure (1); lung adenocarcinoma (1); lung squamous cell carcinoma (1); metastatic disease (1); necrotizing enterocolitis (1); neuroblastoma (1); Oral Cancer (1); oral lichen planus (1); papillary renal cell carcinoma (1); Polyuria (1).
A further 10 diseases each share a sentence with OSR1 in 1 paper.